METTL15 (methyltransferase 15, mitochondrial 12S rRNA N4-cytidine)
Description:
N4-methylcytidine (m4C) methyltransferase responsible for the methylation of position C839 in mitochondrial 12S rRNA. Involved in the stabilization of 12S rRNA folding, therefore facilitating the assembly of the mitochondrial small ribosomal subunits.
Synonyms: METT5D1; FLJ33979
Tractability: Small molecule: a structure with a bound ligand is known. PROTAC: ubiquitination databases record sites on it; its protein half-life has been measured.
Gene: Protein-coding gene on chromosome 11 (28,108,248 to 28,527,041, forward strand). Ensembl gene ENSG00000169519.
Subcellular location: Mitochondrion matrix
Gene Ontology:
Molecular function: protein binding; rRNA (cytosine-N4-)-methyltransferase activity; methyltransferase activity
Biological process: mitochondrial small ribosomal subunit assembly; rRNA base methylation
Cellular component: methyltransferase complex; mitochondrial matrix; mitochondrion
Genetic constraint (gnomAD): Loss-of-function variants: 33 observed, 36.34 expected, observed/expected ratio (o/e) 0.91, 90% interval 0.69 to 1.21. The upper end of that interval is the gene's LOEUF score, 1.21, which puts it in group 5 of 6, group 1 being the genes least tolerant of losing a copy. Missense variants: 413 observed, 461.15 expected, observed/expected ratio (o/e) 0.9, 90% interval 0.82 to 0.97. Synonymous variants: 155 observed, 156.83 expected, observed/expected ratio (o/e) 0.99, 90% interval 0.87 to 1.13.
Homologues: Orthologues: chimpanzee METTL15 (99% identical), macaque METTL15 (97% identical), pig METTL15 (87% identical), rabbit METTL15 (87% identical), dog METTL15 (86% identical), rat Mettl15 (80% identical), mouse Mettl15 (78% identical), guinea pig METTL15 (78% identical), tropical clawed frog mettl15 (56% identical), zebrafish mettl15 (50% identical), Drosophila melanogaster CG14683 (38% identical).
Diseases named in the same sentence as METTL15 in open-access papers:
METTL15 is named in the same sentence as 9 diseases in open-access papers, as found by Europe PMC text mining. Sharing a sentence is not in itself a finding about the gene and the disease. The quoted sentences say what the papers report.
lung carcinoma (2 papers, 2024). "METTL15 silencing inhibits lung cancer cell proliferation, colony formation, invasion, immune escape and promotes apoptosis." (PMID 39289775, 2024). "circ-METTL15 is overexpressed in lung cancer cells and tissues, and silencing it reduces lung cancer malignancy." (PMID 39051062, 2024). "METTL15 expression is up-regulated in lung cancer tissues and cells." (PMID 39289775, 2024).
Obesity (2 papers, 2022 to 2023). Accumulation of substantial excess body fat. "In contrast, METTL15, zinc finger CCCH-type containing 13 (ZC3H13), fat mass and obesity-associated (FTO), leucine-rich pentatricopeptide repeat containing (LRPPRC), and RNA-binding motif protein 15B (RBM15B) showed widespread CNV frequency loss." (PMID 34979500, 2022). "Other genes related to obesity and/or adipogenesis were identified by our HiChIP analysis as regulators of ABD vs. GF gene transcription, such as METTL15 and RBM4." (PMID 38203607, 2023).
Anxiety (1 paper, 2022). Intense feelings of nervousness, tension, or panic often arise in response to interpersonal stresses. "We subjected the Mettl15−/− knockout mice to the open field test for general exploratory activity and preference for exploration of a new object, and the light–dark box test to assess anxiety and learning." (PMID 35682734, 2022).
cancer (2 papers, 2024 to 2025). A tumor composed of atypical neoplastic, often pleomorphic cells that invade other tissues. "Subsequently, functional assays proved that circ-METTL15 silencing impaired the malignancy of cancer cells, while circ-METTL15 overexpression stimulated PTC malignant progression, hinting that circ-METTL15 could not only be a promising diagnostic biomarker but also a therapeutic target for PTC." (PMID 39051062, 2024).
cardiovascular disease (1 paper, 2025). "METTL15 (Methyltransferase Like 15), involved in mitochondrial RNA methylation, underscores the importance of mitochondrial integrity in cardiovascular disease." (PMID 41299637, 2025).
tumor (1 paper, 2024). "The clinical information table indicated that circ-METTL15 was related to the tumor size, tumor, node, and metastasis (TNM) stage, and N stage." (PMID 39051062, 2024). "Moreover, the high expression of circ-METTL15 was related to the tumor size, TNM stage, and N stage." (PMID 39051062, 2024).
METTL15 also shares sentences with these, for which no sentence is quoted: glioma (1 paper); papillary thyroid cancer (1); Sepsis (1).